PVT1 (Pvt1 oncogene)
Diseases named in the same sentence as PVT1 in open-access papers (continued):
Sharing a sentence is not in itself a finding about the gene and the disease.
systemic lupus erythematosus (4 papers, 2019 to 2025). An autoimmune multi-organ disease typically associated with vasculopathy and autoantibody production. "For the systemic lupus erythematosus pathway, the majority of genes linked to PVT1 are histone-coding genes." (PMID 31710657, 2019). "Intriguingly, identified associations of PVT1 to cellular pathways demonstrate possible links between inferred mechanisms of regulation of gene expression by PVT1 in HIV latency and other diseases, such as basal cell carcinoma and systemic lupus erythematosus." (PMID 31710657, 2019). "Pvt1 suppression skews immunity toward Th1/Treg dominance (pro-inflammatory resolution), while its overexpression exacerbates Th2/Th17 bias (pro-inflammatory amplification), directly disrupting CD4+ T cell homeostasis in lupus." (PMID 40493320, 2025).
viral infection (4 papers, 2016 to 2024). "Moreover, among the top 10 enriched pathways in the KEGG analysis, the majority were associated with viral infections, further emphasizing the impact of PVT1 on the type I interferon signaling pathway." (PMID 38287522, 2024). "In fact, it has been described that Hepatitis B virus genome integrates in the region located between MYC and PVT-1 in 12.4% of HCCs that develop early after viral infection and that viral integration correlates with upregulation of MYC and PVT-1, and, most probably, with the development of HCC." (PMID 29033906, 2017). "Whereas the downregulation of lncRNA PVT1 seems to protect pancreatic β cells from injury, both up-regulated MALAT1 and NEAT1 had been related to inflammatory mediators (TNF-alpha, IL-6, CXCL10), SLE pathogenesis and innate immune response against viral infections." (PMID 35058920, 2021).
astrocytoma (3 papers, 2013 to 2024). "In pediatric midline gliomas and astrocytomas with K27M mutations, MYC/PVT1 also exhibited copy number amplification and patients with this subtype experienced a poorer prognosis." (PMID 38287522, 2024). "GBM demonstrated a significant higher CYTOR and PVT1 expression levels than astrocytoma (A, P <0.001), and oligodendroglioma (OD, P <0.001)." (PMID 29108264, 2017). "GBM displayed remarkably higher PVT1 and CYTOR expression as compared with oligodendroglioma (P =0.002 and P <0.001), oligoastrocytoma (P =0.015 and P =0.002), and astrocytoma (P =0.011 and P <0.001)." (PMID 29108264, 2017).
benign prostatic hyperplasia (3 papers, 2019 to 2021). A non-cancerous nodular enlargement of the prostate gland. "Through histopathological analysis, we confirmed that PCa tissues obtained from sub-Saharan African Black males significantly overexpressed PVT1 exons 4A and 4B in PCa tissues in comparison to benign prostatic hyperplasia and normal prostate tissues." (PMID 32358016, 2020). "We further investigated levels of gene expression of PVT1 exons 4A and 4B and observed significant overexpression of these exons in PCa tissues relative to benign prostatic hyperplasia and to normal prostate tissues obtained from men of African ancestry." (PMID 32358016, 2020). "Our results confirmed significant overexpression of PVT1 exons 4A and 4B in PCa tissues in comparison to normal prostate tissue and benign prostatic hyperplasia." (PMID 32358016, 2020).
breast tumor (3 papers, 2017 to 2024). "The expression of the PVT1 gene correlated with MYC expression in human breast tumors according to Pearson correlation analysis of data obtained from 4307 patients." (PMID 38556549, 2024). "Human microRNA-1204, which is residing in 60 kb downstream of MYC and within the exon 1b of PVT1, depresses tumor suppressor genes and contributes to ovarian and breast tumor proliferations and patients’ survival." (PMID 29079774, 2017). "Summary figures for SE regions near VMP1/MIR21 (Chr 17), SUMO1P1 (Chr 20), and PVT1 (Chr 8) are shown as representative examples from cluster A, B, and D, respectively, showing higher accessibility in non-basal compared with basal breast tumor samples." (PMID 38625038, 2024).
cervical squamous cell carcinoma (3 papers, 2017 to 2021). A squamous cell carcinoma arising from the cervical epithelium. "ROC curve analysis was performed to evaluate the diagnostic values of serum PVT1 for cervical squamous cell carcinoma." (PMID 29760583, 2018). "Besides that, serum PVT1 also showed promising diagnostic and prognostic values for cervical squamous cell carcinoma." (PMID 29760583, 2018). "Serum PVT1 can serve as a promising diagnostic and prognostic biomarker for cervical squamous cell carcinoma PVT1 siRNA silencing inhibited the proliferation of cancer cells and reduced the expression of TGF-β1, while PVT1 overexpression played an opposite role." (PMID 29760583, 2018). "In addition, the diagnostic and prognostic values of serum PVT1 for cervical squamous cell carcinoma were analyzed." (PMID 29760583, 2018). "Serum levels of PVT1 were significantly higher in cervical squamous cell carcinoma patients than in healthy controls." (PMID 29760583, 2018). "Effects of PVT1 siRNA silencing and overexpression on proliferation of cervical squamous cell carcinoma cells were explored by CCK-8 assay." (PMID 29760583, 2018). "Our data have showed that serum levels of PVT1 were abnormally increased in patients with cervical squamous cell carcinoma." (PMID 29760583, 2018). "Overall survival of cervical squamous cell carcinoma patient with high serum level of PVT1 was significantly shorter that that of patients with low serum level of PVT1 (p < 0.05)." (PMID 29760583, 2018). "Expression level of PVT1 was significantly higher in two cervical squamous cell carcinoma cell lines than in two normal cells." (PMID 29760583, 2018). "The area under the curve of serum PVT1 in the diagnosis was 0.9030 with 95% confident interval of 0.8567–0.9472 (p < 0.0001), indicating that serum PVT1 is an accurate biomarker for cervical squamous cell carcinoma." (PMID 29760583, 2018). "In contrast, PVT1 overexpression significantly promoted cell proliferation of two cervical squamous cell carcinoma cell lines." (PMID 29760583, 2018). "Effects of PVT1 siRNA silencing and overexpression on proliferation of cervical squamous cell carcinoma cells and expression of TGF-β1 were also explored." (PMID 29760583, 2018). "PVT1 siRNA silencing and overexpression cell lines were established to investigate the role of PVT1 in the proliferation of cervical squamous cell carcinoma cells." (PMID 29760583, 2018). "In this study, expression of PVT1 in serum of patients with cervical squamous cell carcinoma was detected, and serum levels of PVT1 were compared among patients infected with different HPVs and in different stages of primary tumors." (PMID 29760583, 2018). "Consistent with previous studies, in this study, expression level of PVT1 was found to be significantly higher in cervical squamous cell carcinoma patients than in normal controls." (PMID 29760583, 2018). "Serum levels of PVT1 were significantly increased with the increased sizes of cervical squamous cell carcinoma." (PMID 29760583, 2018). "PVT1 siRNA silencing significantly inhibited cell proliferation of two cervical squamous cell carcinoma cell lines." (PMID 29760583, 2018). "Our study aimed to investigate the role of lncRNA PVT1 in cervical squamous cell carcinoma." (PMID 29760583, 2018). "However, the roles of PVT1 in cervical squamous cell carcinoma still haven’t been well studied." (PMID 29760583, 2018). "Therefore, it will be reasonable to hypothesize that PVT1 may regulate TGF-β1 to participate in cervical squamous cell carcinoma." (PMID 29760583, 2018). "Expression of PVT1 in human cervical squamous cell carcinoma cell lines SiHa (HPV positive) and C33A (HPV negative) and normal cervical cell lines Ect1/E6E7 (HPV positive) and HCvEpC (HPV negative) was detected by qRT-PCR." (PMID 29760583, 2018). "In conclusion, expression of PVT1 in patients with cervical squamous cell carcinoma was not affected by HPV infection." (PMID 29760583, 2018).
cervical squamous cell carcinoma (continued). "In this study, treatment with TGF-β1 (10 ng/ml, Sigma-Aldrich, USA) for 1 h not significantly inhibited cell proliferation of two cervical squamous cell carcinoma cell lines, but also significantly reduce the enhancing effects of PVT1 overexpression on cell proliferation." (PMID 29760583, 2018). "So we conclude that lncRNA PVT1 can promote the growth HPV positive and negative cervical squamous cell carcinoma by inhibiting TGF-β1." (PMID 29760583, 2018). "LncRNA PVT1 promotes the growth HPV positive and negative cervical squamous cell carcinoma by inhibiting TGF-β1." (PMID 29760583, 2018).
colorectal tumors (3 papers, 2019 to 2022). "We found six alternative transcripts of PVT1 in the pooled RNA samples of colorectal tumor and normal tissue samples." (PMID 36052265, 2022). "Precisely, CACO2, SW480, SW620, HT29, and HCT116 cells derived from human colorectal tumors displayed higher levels of total PVT1 compared to NCM460, FHC and HCoEpiC normal colonic epithelial cells." (PMID 32083000, 2020). "No reports are found in the literature regarding the role of PVT1 in sponging miR-152 in colorectal tumors." (PMID 32083000, 2020). "Nonetheless, multiple studies assessing PVT1 expression by means of microarray technology or RT-PCR using oligonucleotides amplifying several PVT1 isoforms, have shown a general overexpression of PVT1 in colorectal tumors compared to paired normal tissue samples." (PMID 32083000, 2020).
gastric tumor (3 papers, 2020 to 2021). "PVT1 isoform Sv-214 overexpression was found in primary gastric tumor samples compared to adjacent normal gastric tissue." (PMID 32083000, 2020). "Precisely, PVT1 expression in gastric tumors enhances microvessel formation, both in vitro and in vivo, through a mechanism that involves vascular endothelial growth factor A (VEGFA) expression in a STAT3-dependent manner." (PMID 32083000, 2020). "Similarly, increased PVT1 expression has been described in primary gastric tumors compared to the normal gastric mucosa." (PMID 32083000, 2020). "Interestingly, in primary gastric tumors PVT1 correlates positively with EZH2 and negatively with p15/p16 protein levels." (PMID 32083000, 2020). "The siRNAs often used to achieve downregulation of PVT1 target multiple transcripts, and not always those predominantly expressed in colorectal and gastric tumors." (PMID 32083000, 2020).
Hyperglycemia (3 papers, 2011 to 2024). An increased concentration of glucose in the blood. "Taken together, these findings strongly implicated that inhibition of PVT1 alleviated mitochondrial dysfunction and inflammation in podocytes provoked by hyperglycemia in vitro." (PMID 39349450, 2024). "To further determine the functions of PVT1 in podocytes under hyperglycemia conditions, we constructed PVT1 ASO lentivirus." (PMID 39349450, 2024). "We also found a pronounced increase of fluorescence intensity of mtROS in hyperglycemia-treated podocytes, in contrast, PVT1 suppression prevented HG-induced mtROS accumulation." (PMID 39349450, 2024). "Concomitantly, suppression of PVT1 by ASO restored the protein levels of AMPKα under hyperglycemia conditions, in contrast overexpressed TRIM56 abolished the effect of PVT1 ASO on AMPKα." (PMID 39349450, 2024). "Notably, immunoblotting analysis showed that the overexpression of TRIM56 attenuated the reno-protective effect of PVT1 ASO on mitochondrial function in the context of hyperglycemia." (PMID 39349450, 2024). "One of the more important findings of this work was that PVT1 effects on expression of FN1, COL4A1, and PAI-1 may be mediated independently of TGFB1, a well-known profibrotic factor which promotes tissue fibrosis by upregulating genes encoding ECM proteins in response to hyperglycemia." (PMID 21526116, 2011). "The present study demonstrates that silencing of PVT1 did not significantly reduce hyperglycaemia in diabetic mice but did suppress the decline in insulin levels." (PMID 36359234, 2022).
mesothelioma (3 papers, 2013 to 2024). A usually malignant and aggressive neoplasm of the mesothelium which is often associated with exposure to asbestos. "Most of these SNPs were located in regions reported to harbor aberrant alterations in mesothelioma (SLC7A14, THRB, CEBP350, ADAMTS2, ETV1, PVT1 and MMP14 genes), causing at most a 2–3-fold increase in MPM risk." (PMID 23626673, 2013).
myocardial ischemia (3 papers, 2021 to 2024). A disorder of cardiac function caused by insufficient blood flow to the muscle tissue of the heart. "Lately, silencing lncRNA plasmacytoma variant translocation 1 (PVT1) has been demonstrated to mitigate myocardial ischemia–reperfusion (I/R) damage via suppressing GSDMD‐mediated pyroptosis." (PMID 39320020, 2024).
Nephropathy (3 papers, 2019 to 2022). A nonspecific term referring to disease or damage of the kidneys. "Secondly, the renoprotection of PVT1 silencing on female mice was likely yet unreported, as only male C57BL/6 mice were used, which are more susceptible to kidney damage." (PMID 36359234, 2022).
Obesity (3 papers, 2022 to 2024). Accumulation of substantial excess body fat. "Considering the key role of PVT1 in affecting angiogenesis and regulating obesity, PVT1 may be a potential candidate gene related to EH risk." (PMID 35036445, 2022). "The plasmacytoma variant translocation 1 (PVT1) is involved in modulating angiogenesis in tumor tissues and plays an important role in fat differentiation in the progress of obesity." (PMID 35036445, 2022). "Furthermore, recent studies have shown that PVT1 was found to be a potential biomarker for obesity treatment." (PMID 35036445, 2022).
ovarian tumors (3 papers, 2011 to 2021). "Collectively, these results reveal that deletion of the high level of PVT1 or AGO1 slowed the ovarian tumour growth in vivo." (PMID 34288373, 2021). "PVT1 or AGO1 knockdown significantly reduced the cell viability and increased the cell apoptosis and inhibited ovarian tumour growth and proliferation." (PMID 34288373, 2021).
parathyroid carcinoma (3 papers, 2021 to 2025). "LncRNA score was still found to be an independent risk factor of parathyroid cancer independent from PVT1." (PMID 33910638, 2021). "On the other hand, LncRNA plasmacytoma variant translocation 1 (PVT1) also might play a role in parathyroid carcinoma." (PMID 33910638, 2021). "PVT1 was an independent risk factor of parathyroid cancer when adjusted by male, age and iPTH." (PMID 33910638, 2021). "Using quantitative real-time polymerase chain reaction (RT-qPCR), expression profile of PVT1 was evaluated in 57 patients with primary hyperparathyroidism, including 11 with parathyroid cancer (PC) and 46 with parathyroid adenoma (PA)." (PMID 33910638, 2021). "Taken together, PVT1 may participate in parathyroid cancer development through EZH2 pathway." (PMID 33910638, 2021).
schizophrenia (3 papers, 2021 to 2025). A major psychotic disorder characterized by abnormalities in the perception or expression of reality. "We have recently demonstrated down-regulation of FAS-AS1, PVT1, and TUG1 in patients with schizophrenia compared with controls." (PMID 34220567, 2021). "While Gomafu, PINT, GAS5, TCONS_l2_00021339, IFNG-AS1, FAS-AS1, PVT1, and TUG1 are among down-regulated lncRNAs in schizophrenia, MEG3, THRIL, HOXA-AS2, Linc-ROR, SPRY4-IT1, UCA1, and MALAT1 have been up-regulated in these patients." (PMID 34220567, 2021).
stomach carcinoma (3 papers, 2017 to 2023). "Overexpression of lncRNA PVT1 in gastric carcinoma promoted the development of multidrug resistance and influenced the expression of MDR-related proteins (MDR1, MRP1, mTOR, and HIF-1a)." (PMID 29046366, 2017).
urothelial bladder carcinoma (3 papers, 2017 to 2024). "Additionally, the overexpression of lncRNA plasmacytoma variant translocation 1 (PVT1) in multidrug-resistant urothelial bladder carcinoma tissues and cell lines is linked to increased cell proliferation, invasion, and chemoresistance." (PMID 38249783, 2024).
acute erythroleukemia (2 papers, 2018 to 2022). "Here, we performed blockage of lncRNA PVT1 in human acute erythroleukemia (AEL) cell line (KG1) using antisense LNA GapmeRs." (PMID 30046623, 2018). "In the present study, we have used antisense LNA GapmeRs to inhibit lncRNA PVT1 in acute erythroleukemia (AEL, also known as AML M6) cell line (KG-1) and its effects on the apoptosis and necrosis of KG-1 cells were assessed." (PMID 30046623, 2018). "Early reports have demonstrated that PVT1 is significantly upregulated in peripheral blood cells from patients with APL and acute erythroleukemia (AEL)." (PMID 35152842, 2022).
acute pancreatitis (2 papers, 2022). An acute inflammatory process that leads to necrosis of the pancreatic parenchyma. "Hu et al7 demonstrated that PVT1 promotes the development of acute pancreatitis by inducing autophagy activation of pancreatic acinar cells by regulating mir-30A-5p/Beclin-1 axis." (PMID 35723715, 2022).
adenoma (2 papers, 2020 to 2025). A neoplasm arising from the epithelium. "Plasmacytoma variant translocation 1 (PVT1) is a lncRNA that was found to be overexpressed in adenoma cells in vitro." (PMID 32498309, 2020).
atrial fibrillation (2 papers, 2019 to 2025). A disorder characterized by an electrocardiographic finding of a supraventricular arrhythmia characterized by the replacement of consistent P waves by rapid oscillations or fibrillatory waves that vary in size, shape and timing and are accompanied by an irregular ventricular response. "The role of long non-coding RNA plasmacytoma variant translocation 1 (PVT1) was assessed in atrial fibrillation." (PMID 39506064, 2025). "Atrial muscle tissue from patients with atrial fibrillation demonstrated an increase in PVT1, which correlated with an increase in collagen I and collagen III." (PMID 39506064, 2025). "LncRNA PVT1 promotes atrial fibrosis via miR-128-3p-SP1-TGF-β1-Smad axis in atrial fibrillation." (PMID 30894138, 2019).
Atrophy (2 papers, 2019 to 2023). Any weakening or degeneration, especially through lack of use. "We confirmed this mechanism also in atrophy models that show Pvt1 up-regulation." (PMID 30649422, 2019). "Early activation of lncRNA Pvt1 following muscle atrophy affects mitochondrial respiration and morphology and influences autophagy and apoptosis related to mitochondrial conformation and myofiber size, and thus targeting lncRNA Pvt1 may be a viable therapeutic target for muscle atrophy." (PMID 37495991, 2023).
autoimmune disease (2 papers, 2021 to 2025). A disorder resulting from loss of function or tissue destruction of an organ or multiple organs, arising from humoral or cellular immune responses of the individual to their own tissue constituents. "Numerous studies suggest that aberrant expression of lncRNA PVT1 may contribute to the pathogenesis of autoimmune diseases." (PMID 40493320, 2025).
chronic myelogenous leukemia (2 papers, 2019 to 2022). "On the imputed contact maps for the chronic myelogenous leukemia cell K562, MYC gene strongly interacts with PVT1, which matches with the peaks of CRISPRi scores at PVT1 locus." (PMID 35440119, 2022).
Cognitive impairment (2 papers, 2017 to 2018). Abnormal cognition is characterized by deficits in thinking, reasoning, or remembering. "Intriguingly, activation of PVT1 by autophagy could protect against hippocampal neuron injury and ultimately ameliorate cognitive impairment in diabetic mice." (PMID 30126849, 2018). "For instance, previous research found that PVT1-mediated autophagy could protect against hippocampal neuron apoptosis and thereby alleviate cognitive impairment in diabetic mice." (PMID 30126849, 2018).
cutaneous squamous cell carcinoma (2 papers, 2022 to 2023). "However, the expression and associated regulatory mechanisms of PVT1 in cutaneous squamous cell carcinoma (cSCC) remain unclear." (PMID 36944636, 2023).